TLR4 (toll like receptor 4)
Diseases named in the same sentence as TLR4 in open-access papers (continued):
Sharing a sentence is not in itself a finding about the gene and the disease.
pneumonia (continued). "Taken together, XIST may be involved in progression of cell inflammatory response, and XIST/miR‐370‐3p/TLR4 axis thus may shed light on the development of novel therapeutics to the treatment of acute stage of pneumonia." (PMID 31066476, 2019). "TLR2 and TLR4 are crucial for recognition of Chlamydia pneumoniae in vivo, since infected TLR2/4 double-deficient mice are unable to control the infection as evidenced by severe loss of body weight and progressive lethal pneumonia." (PMID 22096480, 2011). "In line with the stimulatory effect of LPS and CpG on sCD14 release by PBMCs, we speculate that sCD14 levels in patients with pneumonia might be mainly induced via the TLR4 and TLR9 ligands LPS and CpGs, respectively." (PMID 20302606, 2010). "In addition, HMGB1/TLR4, a therapeutic target for severe pneumonia, including COVID‐19, mediates the release of proinflammatory cytokines, and acetylcholine, heparin, statins, glycopyrrolate, ketamine, and resveratrol are important drug candidates as TLR4 inhibitors." (PMID 35923762, 2022). "Therefore, anemoside B4 suppressed the FM1 or KP-induced pneumonia via the TLR4/Myd88 pathway." (PMID 32625244, 2020). "The TLR2, TLR4, and MyD88 deficiency did not alter the host response during lethal pneumonia." (PMID 32849610, 2020). "Previous studies have shown that AB4 alleviates pneumonia induced by Klebsiella pneumoniae and influenza virus FM1 in mice by inhibiting the TLR4/MyD88 signaling pathway." (PMID 40012747, 2025). "Further, we show that antagonism of TLR4 can specifically rescue morbidity in SPARCL1 overexpressing mice, suggesting a potential therapeutic intervention for pneumonia patients with high levels of circulating SPARCL1." (PMID 38762489, 2024). "In our work, inspired by these studies, we aimed to detect the role of XIST in LPS-stimulated pneumonia in WI-38 cells, as well as determine a novel XIST/miR-30b-5p axis regulating TLR4/NF-κB signaling pathway." (PMID 33817304, 2021). "A recent mechanistic investigation revealed that SHNG16 acts as a ceRNA to positively regulate Toll-like receptor 4 (TLR4) and thus affect the LPS-induced inflammatory and immune processes via mediating JNK and NF-κB pathways in pneumonia." (PMID 34290731, 2021). "During pneumonia, AECs recognize various pathogens due to the expression of different PRRs, including TLRs [TLR1, TLR2, TLR4, TLR5, TLR6 (Extracellular TLRs), and TLR3, TLR7, TLR8, and TLR9 (Intracellular TLRs)] and NLRs comprising inflammasome." (PMID 32849610, 2020). "Pneumonia is characterized by the production of inflammation-related cytokines and chemokines throughout the body, especially in the lungs, including TNF- α, IFN- γ, IL-6 and IL-1β which are controlled by TLR4/NF-κB signaling pathway." (PMID 36530439, 2022). "First, while endotoxin is a powerful stimulator of TLR2- and TLR4-mediated immune responses which play key roles in bacterial pneumonia-induced ALI, it does not fully recapitulate pneumonia caused by an infectious and proliferating pathogen." (PMID 36555499, 2022). "The patients who develop post‐operative pneumonia show a trend of significant reduction in TLR4 expression compared with those without pneumonia." (PMID 31350813, 2019). "In conclusion, this study firstly indicated that XIST was increased in serum of patients with acute‐stage pneumonia and LPS‐injured WI‐38 cells; downregulation of XIST attenuated LPS‐induced apoptosis and inflammation in WI‐38 cells via modulating miR‐370‐3p/TLR4 axis." (PMID 31066476, 2019). "After surgery patients who developed postoperative pneumonia revealed a trend of stronger reduction of HLA-DR expression (83.7% versus 27.1%) and TLR4 expression on AMs (46.1% versus 9.9%) compared to patients without pneumonia." (PMID 24321282, 2013).
pneumonia (continued). "Toll-like receptor 4 (TLR4) activation induced immune response protects the experimental animals infected with Gram-positive (Streptococcus pneumoniae) or Gram-negative bacteria (Klebsiella pneumoniae) induced pneumonia." (PMID 32849610, 2020). "Moreover, we found that TLR4 and TLR9 regulate lung IL-23 and IL-17 responses in pneumonia." (PMID 20360853, 2010). "Studies analyzing global responses in pneumonia by using TLR-deficient mice (or C3H/Hej mice, which express a non-functional TLR4), therefore give only limited information on the role of lung epithelial TLR expression in pneumonia." (PMID 16827942, 2006).
renal fibrosis (78 papers, 2011 to 2026). A final common manifestation of a wide variety of chronic kidney diseases characterized by glomerulosclerosis and tubulointerstitial fibrosis. "After being activated by TLR4, NF-κB translocates to the nucleus to induce the expression of specific genes, triggering the massive release of inflammatory factors and causing renal fibrosis." (PMID 38259279, 2023). "AS-IV has been shown to prevent renal fibrosis caused by unilateral ureteral obstruction by reducing the inflammatory response via the TLR4/NF-κB pathway." (PMID 36160396, 2022). "Numerous endogenous ligands have been identified for the activation of TLR4 in DN, and some of them have been shown to be closely associated with inflammation and renal fibrosis." (PMID 32411800, 2020). "One day after unilateral ureteral obstruction, TLR4-deficient mice had more tubular damage and fewer proliferating tubular epithelial cells than WT mice but developed considerably less renal fibrosis." (PMID 28416741, 2017). "Recent evidence indicates that TLR4-mediated inflammation is a critical pathogenic link between innate immunity and renal fibrosis." (PMID 28416741, 2017). "Notably, LPS from Proteobacteria not only disrupts gut barrier integrity but also amplifies systemic inflammation via TLR4/NF-κB signaling, a pathway implicated in renal fibrosis and podocyte injury." (PMID 40458807, 2025). "In renal fibrosis, the loss of Chop gene represses Hmgb1/TLR4 signal pathway, leading to repressed NF-κB transcriptional activity along with suppressed IL-1β production, and reduced TGF-β1 production and PI3K/Akt activity to attenuate the development of fibrosis." (PMID 36357371, 2022). "Previous studies reported that TLR4 is expressed by HRMCs, and high expression of TLR4 may be associated with inflammatory factor production and renal fibrosis." (PMID 32388684, 2020). "The TLR4 signal pathway associated with inflammation and immunity has been uncovered in many diseases, such as intracerebral hemorrhage, osteoarthritis, renal fibrosis, and chronic kidney disease." (PMID 31402870, 2019). "Further, we show that TLR4 may play a role in the recruitment of bone marrow-derived fibroblasts into the kidney via TGF-β activation and TLR4 deficiency suppresses their accumulation to decrease renal fibrosis." (PMID 28743964, 2017). "Two other studies have documented that Tlr4-deficient mice develop less renal fibrosis after UUO." (PMID 21544241, 2011). "Consistently, either knockdown of TNC or knockout of TLR4 in vivo blocks the activation of TLR4/NF‐κB signaling and represses renal inflammation, alleviates renal fibrosis, and preserves renal function." (PMID 41042124, 2026). "Once absorbed, they activate Toll-like receptor 4 (TLR4) and nuclear factor kappa-B (NF-κB) pathways, exacerbating chronic inflammation and oxidative stress—major contributors to renal fibrosis and cardiovascular complications." (PMID 40735439, 2025). "The study by Souza ACP showed TLR4 accelerated, through activation of inflammatory vesicles and dysregulation of the immune response, the progression of renal fibrosis and CKD." (PMID 40584714, 2025). "Deficiency of CHOP can ameliorate renal ischemia-reperfusion injury in mice, and prevents UUO-induced renal fibrosis by attenuating fibrotic signals derived from HMGB1/TLR4/NF-κB/IL-1β signaling." (PMID 41280890, 2025). "We also found that MICT alleviated renal fibrosis and inflammatory response as well as inhibited TLR4/NF-κB pathway and the activation of NLRC4 inflammasome in SHR." (PMID 39052650, 2024). "We believe that the improvement of renal fibrosis in the SHR-M group is related to the inhibition of the TLR4/NF-κB pathway and the reduction of inflammatory cytokine levels." (PMID 39052650, 2024). "MICT ameliorated renal damage, inflammatory response, and renal fibrosis via repressing TLR4/NF-κB pathway and the activation of NLRC4 inflammasome." (PMID 39052650, 2024).
renal fibrosis (continued). "Liraglutide attenuated glomerular hypertrophy, renal fibrosis, and inflammatory response in TLR4−/− diabetic mice." (PMID 39133777, 2024). "The improvement of renal fibrosis and inflammation by deletion of TLR4 was further indicated by significantly less increase in ECM protein and inflammatory factors in TLR4−/− diabetic mice compared with WT diabetic mice." (PMID 39133777, 2024). "MICT improved renal fibrosis and renal injury, attenuating the inflammatory response by inhibiting TLR4/NF-κB pathway and the activation of NLRC4 inflammasome." (PMID 39052650, 2024). "Madbouly found that taurine reduced the deposition of extracellular matrix and improved renal fibrosis by inhibiting the expression of TLR4 in renal tubular epithelial cells." (PMID 37565908, 2023). "The role of TLR4 signaling in modifying the ECM and fibrotic environment has been studied in hepatic and renal fibrosis, scleroderma, as well as in Tlr4 mutant mice." (PMID 36911656, 2022). "Recently, Astragaloside IV has been proven to ameliorate renal fibrosis by inhibiting inflammation via the toll-like receptor 4 (TLR4)/NF-кB signaling pathway in UUO mice." (PMID 36408254, 2022). "MSCs were discovered to have an anti-inflammatory effect on renal fibrosis by suppressing the activation of the TLR4 signaling pathway." (PMID 35841116, 2022). "Using small interfering RNA, we assessed the effect of BYF on the TLR4-mediated NF-κB mechanism for CKD renal fibrosis and inflammation." (PMID 34867380, 2021). "It has been shown that TLR4 was involved in renal fibrosis by mediating pro-inflammatory and pro-fibrotic pathways." (PMID 34338139, 2021). "Mutation of TLR4 protects mice from development of inflammation and renal injury including albuminuria, glomerulosclerosis, and renal fibrosis after nephrectomy with angiotensin II infusion, as revealed by C3HeJ TLR4 mutant mice." (PMID 32660446, 2020). "Increasing evidences propose that TLR4 activation is closely involved in the inflammatory process and renal fibrosis of DN." (PMID 32411800, 2020). "It has been reported that TLR4 mediates both pro-inflammatory and pro-fibrotic pathways in renal fibrosis." (PMID 30836660, 2019). "On the other hand, TLR4 attenuates tubular damage and does contribute to renal fibrosis during obstructive nephropathy as demonstrated by an increased injury score and decreased collagen deposition in TLR4-deficient mice." (PMID 29609537, 2018). "Our results suggest that hucMSC-CM has protective effects against UUO-induced renal fibrosis and that hucMSC-CM exhibits its anti-inflammatory effects through inhibiting TLR4/NF-κB signaling pathway activation." (PMID 29329595, 2018). "Our results showed that relaxin can downregulate the TLR4-NF-κB signaling pathway, shift macrophage polarization toward the M2 phenotype and ameliorate renal fibrosis at the early stages of UUO." (PMID 28416741, 2017). "Their studies suggest that UUO can induce a dramatic increase in TLR4 expression, therefore promoting renal fibrosis." (PMID 28416741, 2017). "Our experiments also show a decrease in renal fibrosis in line with previous reports on CHOP knockouts; CHOP deficiency attenuated Tlr4, NF-κB, and TGF-β activity in response to Ang II/DOCA salt." (PMID 28148966, 2017). "Increased TLR4 expression contributes to renal fibrosis and CKD progression via inflammasome activation in renal epithelial cells." (PMID 28665028, 2017). "In experimental hyperaldosteronism, upregulation of TLR4 is correlated with cardiac and renal fibrosis and dysfunction, and a TLR4 signaling antagonist, TAK-242, can reverse these alterations." (PMID 26556241, 2015). "We first tested the role of TLR4 on renal fibrosis using a folic acid model where mice develop tubulointerstitial damage and fibrosis following recovery from folic acid-induced tubular necrosis and acute renal injury." (PMID 26416975, 2015).
renal fibrosis (continued). "In a model of renal fibrosis after folic acid injection, TLR4 mutant mice developed less interstititial fibrosis in comparison to wild-type (WT) mice." (PMID 26416975, 2015). "In this study we tested the role of Toll-like receptor 4, the main receptor for endotoxin (LPS), in a mouse model of renal fibrosis and in a model of progressive CKD that better resembles the human disease." (PMID 26416975, 2015). "In this study we show that, in vivo, TLR4 mutant mice are protected from renal fibrosis following folic acid injection, and also from progressive CKD in a low-dose angiotensin II infusion (AngII) + 5/6 nephrectomy model." (PMID 26416975, 2015). "TLR4−/− mice subjected to unilateral ureteral obstruction showed less renal fibrosis compared to WT counterparts." (PMID 24842252, 2014). "Instead, we performed a mutation analysis of the TLR4 gene, because it has been thought that TLR4 is involved in progressive renal fibrosis." (PMID 22443450, 2012). "The unilateral ureteral obstruction (UUO) model is often used in the context of renal fibrosis and data from TLR2– or TLR4-deficient mice propose that TLR signaling contributes to postobstructive renal inflammation, tubular atrophy, and interstitial fibrosis." (PMID 21544241, 2011). "Substantial evidence has shown that renal fibrosis is linked to hyperactive pro-fibrotic molecular players, such as the renin-angiotensin system (RAS), reactive oxygen species (ROS), Toll-like receptor 4 (TLR4), and aryl hydrocarbon receptor (AHR) 22-25." (PMID 41522358, 2026). "Moreover, liraglutide still appropriately alleviated glomerular hypertrophy, renal fibrosis, and inflammatory response in TLR4−/− DM mice." (PMID 39133777, 2024). "We investigated whether the improvement effects of exercise training on renal fibrosis was related to the TLR4 signaling pathway considering the crucial role of the TLR4/NF-κB pathway in inflammatory response." (PMID 39052650, 2024). "In addition, there is strong evidence that TLR4 play distinct roles in the pathogenesis of renal fibrosis." (PMID 36361652, 2022). "Studies have confirmed that salidroside reduces excessive deposition of ECM, prevents epithelial cell EMT, and ameliorates renal fibrosis by inhibiting the expression of TLR4/MAPK/NF-κB signaling pathway and its downstream pro-inflammatory and pro-fibrotic factors." (PMID 35978370, 2022). "Successful inhibition of TLR4/NFκB signaling in fibroblast-like cells has been demonstrated in vitro by administration of miR-146, which also inhibits pro-fibrotic and inflammatory signaling pathways in renal fibrosis in vivo." (PMID 34073556, 2021). "Also, these results showed that BYF alleviated renal fibrosis and inflammation via TLR4/NF-κB signaling pathway modulation." (PMID 34867380, 2021). "Altogether, these results demonstrated that the BYF might have a protective effect via the TLR4-mediated NF-κB mechanism to reduce CKD renal fibrosis and inflammation." (PMID 34867380, 2021). "Altogether, our study demonstrated that BYF reduced renal fibrosis and inflammation by TLR4-mediated NF-κb signaling pathway suppression, which may be a key mechanism of its therapeutic effect on CKD." (PMID 34867380, 2021). "Our results indicated that BYF could significantly reduce renal fibrosis and inflammation by TLR4/NF-κB signaling pathway inhibition." (PMID 34867380, 2021). "In addition, further studies demonstrate that both RAS components and TLR4 signaling pathway attend in the regulation of inflammation during kidney injury and renal fibrosis." (PMID 32411800, 2020). "Previous studies have shown that activation of the TLR4/NF-κB signaling pathway can cause interstitial inflammation, which in turn leads to renal interstitial fibrosis, and inhibition of TLR4/NF-κB pathway activation can inhibit the progression of renal fibrosis." (PMID 29329595, 2018).